RNU6-468P (RNA, U6 small nuclear 468, pseudogene)
Gene: Small nuclear RNA gene on chromosome 17 (17,578,631 to 17,578,739, forward strand). Ensembl gene ENSG00000206730.
Homologues: Orthologues: chimpanzee U6 (98% identical), rat U6 (89% identical), rabbit U6 (88% identical), macaque U6 (85% identical). Paralogues in human: RNU6-38P (93% identical), RNU6-25P (91% identical), RNU6-33P (91% identical), RNU6-698P (91% identical), RNU6-891P (91% identical), RNU6-1 (90% identical), RNU6-2 (90% identical), RNU6-20P (90% identical), RNU6-3P (90% identical), RNU6-476P (90% identical), RNU6-48P (90% identical), RNU6-4P (90% identical), and 1284 more.